IFI27L2 (interferon alpha inducible protein 27 like 2)
Description:
Plays a role in the apoptotic process and has a pro-apoptotic activity.
Synonyms: ISG12B; FAM14A; TLH29
Tractability: Antibody: UniProt predicts a signal peptide or a membrane-spanning region.
Gene: Protein-coding gene on chromosome 14 (94,125,580 to 94,130,253, reverse strand). Ensembl gene ENSG00000119632.
Subcellular location: Mitochondrion membrane
Subcellular location (Human Protein Atlas): Cytosol; Nucleoli
Gene Ontology:
Molecular function: molecular adaptor activity
Biological process: apoptotic process; intrinsic apoptotic signaling pathway
Cellular component: mitochondrial membrane; mitochondrion; membrane
Genetic constraint (gnomAD): Loss-of-function variants: 9 observed, 8.69 expected, observed/expected ratio (o/e) 1.04, 90% interval 0.62 to 1.72. That is too few expected variants to judge how well the gene tolerates losing a copy. Missense variants: 190 observed, 174.71 expected, observed/expected ratio (o/e) 1.09, 90% interval 0.96 to 1.23. Synonymous variants: 56 observed, 69.84 expected, observed/expected ratio (o/e) 0.8, 90% interval 0.65 to 1.
Homologues: Orthologues: chimpanzee IFI27L2 (98% identical), macaque IFI27L2 (91% identical), dog IFI27L2 (64% identical). Paralogues in human: IFI27L1 (49% identical), IFI27 (45% identical), IFI6 (35% identical).
Diseases named in the same sentence as IFI27L2 in open-access papers:
IFI27L2 is named in the same sentence as 5 diseases in open-access papers, as found by Europe PMC text mining. Sharing a sentence is not in itself a finding about the gene and the disease. The quoted sentences say what the papers report.
Stroke (2 papers, 2023 to 2025). Sudden impairment of blood flow to a part of the brain due to occlusion or rupture of an artery to the brain. "Immunohistochemistry showed significant IFI27L2 expression in the stroke brain samples but low expression in age-matched control samples (representative of n = 2–3)." (PMID 36824976, 2023). "Elevated IFI27L2 (human isoform) was also found in plasma of human stroke patients." (PMID 41041541, 2025).
virus infections (1 paper, 2021). "IFNα-inducible protein 6 (IFI6, aka IFI-6-16, or GIP3) is a member of a conserved protein family that consists of IFI6, IFI27 (ISG12a), IFI27L1 (ISG12c), and IFI27L2 (ISG12b), and it was first characterized as a cellular gene induced by the IFN response and virus infections." (PMID 34205058, 2021).
infection (3 papers, 2013 to 2025). The state of being infected such as from the introduction of a foreign agent such as serum, vaccine, antigenic substance or organism. "In all cases, the minor frequency “alternative” allele was associated with higher gene expression as well as better survival after VNN infection, and it showed a clear significant (p ≤ 2.9E07) additive effect, with heterozygous animals showing intermediate expression of IFI27L2/2A genes." (PMID 40069747, 2025). "IFI27L2A is upregulated in response to VNN in European sea bass, and in fact an IFI27L2-encoding gene (FN665389.1), corresponding to LOC126358685, has been used since 2010 in several studies to monitor the response to either VNN infection or vaccination in this species." (PMID 40069747, 2025). "Genes relating to inflammation, repair, apoptosis and antiviral responses (e.g., IFI27L2, IFIT5, CXCL10-like,) were upregulated in the per-acute phase of infection (1–3 dpi) and continually increased in its transcription to 4–6 dpi." (PMID 40758745, 2025). "Therefore, we hypothesized that IFN might be induced during early infection, as indicated by the subsequent enhanced production of ISGs because increased expression of a variety of ISGs, such as OSAL, MX1, IFIT5, ISG12-2, RSAD2, IFI35, protein kinase R (PKR), and IFI27L2, was found in this study." (PMID 24168272, 2013).
IFI27L2 also shares sentences with these, for which no sentence is quoted: cancer (1 paper); lung carcinoma (1).